CD200 (CD200 molecule)
Diseases named in the same sentence as CD200 in open-access papers (continued):
Sharing a sentence is not in itself a finding about the gene and the disease.
epilepsy (2 papers, 2021 to 2023). A brain disorder characterized by episodes of abnormally increased neuronal discharge resulting in transient episodes of sensory or motor neurological dysfunction, or psychic dysfunction. "Tll1, dopamine receptor D2 (Drd2) and cluster of differentiation 200 (Cd200) were selected because of their reported link to epilepsy, shared interactions and molecular functions." (PMID 33584828, 2021).
large cell neuroendocrine carcinoma (2 papers, 2021 to 2025). A usually aggressive carcinoma composed of large malignant cells which display neuroendocrine characteristics. "CD200 positivity was observed in 29.7% of patients with NSCLC and 33.3% of patients with lung large cell neuroendocrine carcinoma (LCNEC)." (PMID 41417784, 2025). "CD200 tumor positivity was found in 29.7% of non-small cell lung cancer (NSCLC) patients and 33.3% of lung large cell neuroendocrine carcinoma (LCNEC) patients." (PMID 33804482, 2021).
laryngeal carcinoma (2 papers, 2013 to 2023). Carcinoma that arises from the laryngeal epithelium. "CD200 and CD200R are highly expressed in CD83+ monocyte-derived dendritic cells (Mo-DCs) stimulated with autologous cancer cell lysates from patients with laryngeal cancer compared with unstimulated Mo-DCs." (PMID 37894750, 2023). "Our results prove that there is a relation between the presence of laryngeal cancer and the expression of B7H1, B7H4, CD200, and CD200R regulatory molecules on the CD83+ Mo-DC pulsed with autologous cancer cell lysates." (PMID 23632869, 2013). "Patients with poorly differentiated laryngeal cancer, human pancreatic ductal adenocarcinoma (PDAC), and human clear cell renal cell carcinoma (ccRCC) exhibit elevated CD200 expression, suggesting that it may promote immunosuppression as an immune checkpoint." (PMID 37894750, 2023).
lichen planopilaris (2 papers, 2013 to 2025). Lichen planopilaris (LPP) is an inflammatory condition that causes patchy hair loss, mainly on the scalp. "In conditions such as lichen planopilaris, when immune privilege in the bulge collapses, T cells infiltrate the area and eradicate KRT15+ and CD200+ stem cells, underscoring the sensitivity of these markers to inflammation-driven damage." (PMID 40361941, 2025).
Lymphadenopathy (2 papers, 2021 to 2023). Enlargement (swelling) of a lymph node. "Compared with patients with CD200-negative MCL, those with CD200 + MCL are more likely to have non-nodal leukemic presentation characterized by the loss of lymphadenopathy or extranodal and/or gastrointestinal tract disease." (PMID 34256839, 2021).
medulloblastoma (2 papers, 2014 to 2023). A malignant, invasive embryonal neoplasm arising from the cerebellum. "In addition, CD200 mRNA levels were significantly elevated in the group 4 (sonic hedgehog/cMYC negative) medulloblastoma subset compared to sonic hedgehog positive (SHH+) and group 3 (cMYC+) subsets (p = 0.001 and p = 0.001 respectively)." (PMID 25598973, 2014).
Meningococcal Septicemia (2 papers, 2019 to 2023). "CD200 induction by TLRs and NOD-like receptors has been demonstrated to limit macrophage activation and to protect the host from Meningococcal Septicemia." (PMID 30717437, 2019).
Merkel Cell Carcinoma (2 papers, 2023 to 2025). "This study emphasizes the potential of CD200 as a prognostic biomarker in Merkel cell carcinoma (MCC)." (PMID 40075669, 2025).
metastatic melanoma (2 papers, 2019 to 2023). A melanoma that has spread from its primary site to another anatomic site. "The presence of either endogenous or tumor-expressed CD200 restored the growth of metastatic melanoma foci." (PMID 30653571, 2019).
osteosarcoma (2 papers, 2022 to 2023). A usually aggressive malignant bone-forming mesenchymal neoplasm, predominantly affecting adolescents and young adults. "In addition, DIO3OS may be a novel immunotherapeutic target for osteosarcoma by suppressing immune checkpoints (CD200 and TNFRSF25) and is a novel diagnostic biomarker to distinguish osteosarcoma from multiple other subtypes of sarcoma." (PMID 37752544, 2023). "Therefore, silencing DIO3OS expression may improve the efficacy of osteosarcoma immunotherapy by inhibiting immune checkpoints (CD200 and TNFRSF25)." (PMID 37752544, 2023). "Therefore, knockout DIO3OS may be a novel immunotherapy for patients with osteosarcoma by inhibiting immune checkpoints (CD200 and TNFRSF25)." (PMID 37752544, 2023).
ovarian neoplasm (2 papers, 2019 to 2024). A benign, borderline, or malignant neoplasm involving the ovary. "Our data could be in line with this hypothesis as CD200 is a marker associated not only with neuroendocrine differentiation but also with ovarian neoplasms, highlighting the potential importance of embryogenesis in SPN origin." (PMID 30132130, 2019).
plasmacytoma (2 papers, 2012 to 2020). Plasmacytoma is a localized mass of neoplastic monoclonal plasma cells that represents approximately 5% of all plasma cell neoplasms. "Our previous study has revealed that CD200-positive plasmacytoma J558 and mastocytoma P815 tumors are more susceptible to CTL adoptive transfer therapy presumably due to a more permissive tumor microenvironment." (PMID 22319630, 2012).
Toxoplasma encephalitis (2 papers, 2012 to 2022). "In models of EAE, Toxoplasma encephalitis, experimental autoimmune retinitis, collagen-induced arthritis and influenza-induced pneumonitis, CD200−/− mice show enhanced inflammatory responses." (PMID 23082204, 2012). "For instance, the binding of neuronal CD200 to its microglial receptor CD200R is necessary for restricting microglial activation in disease models including rotenone neurotoxicity and Toxoplasma encephalitis in the absence of this interaction, microglia become reactive and excessively proliferative." (PMID 35346293, 2022).
uveal melanoma (2 papers, 2022 to 2024). A melanoma derived from melanocytes of the uveal tract. "Uveal melanoma can evade immune surveillance via multiple mechanisms, such as inhibitory checkpoint programmed cell death ligand 1 (PD-L1), cluster of differentiation 47 (CD47), and cluster of differentiation 200 (CD200)." (PMID 38732371, 2024). "Uveal melanoma can evade immune surveillance via multiple mechanisms such as the expression of inhibitory checkpoint programmed cell death ligand 1 (PD-L1), cluster of differentiation 47 (CD47), cluster of differentiation 200 (CD200)." (PMID 35741122, 2022).
acute leukemia (1 paper, 2015). A clonal (malignant) hematopoietic disorder with an acute onset, affecting the bone marrow and the peripheral blood. "CD200, a protein belonging to the immunoglobulin superfamily, has been associated with a poor prognosis in lymphoproliferative disorders and in acute leukemia." (PMID 26338961, 2015).
acute respiratory distress syndrome (1 paper, 2022). Progressive and life-threatening pulmonary distress in the absence of an underlying pulmonary condition, usually following major trauma or surgery. "Given the intricacy of CD200/CD200R pathway on controlling immune responses depends on stimuli and tissues, we investigated the role of CD200 in a model of acute respiratory distress syndrome (ARDS) induced by LPS using CD200 knockout (KO) Sprague Dawley rats." (PMID 36591265, 2022).
amyloid (1 paper, 2024). "Consequently, in AD patients with amyloid deposition, the down-regulation of CD200 results in compromised microglial function for Aβ clearance, leading to aggravated amyloid deposition and cognitive decline." (PMID 37801139, 2024).
Arrhythmia (1 paper, 2024). Any cardiac rhythm other than the normal sinus rhythm. "Furthermore, by robustly phenotyping input cell doses and correlating these with the resultant arrhythmia burden, we identify SIRPA+CD90+CD200+ and SIRPA+CD90−CD200− cells as populations of arrhythmogenic and potentially non-arrhythmogenic CMs, respectively." (PMID 39196193, 2024).
atherosclerosis (1 paper, 2021). A disease characterized by the build-up of fatty material and calcium deposition in the arterial wall resulting in partial or complete occlusion of the arterial lumen. "Using atherosclerosis-prone ApoE−/− mice with global or tissue-specific CD200 deficiency, we reveal that CD200 plays a protective role in atherogenesis." (PMID 33975450, 2021). "Next, the effect of CD200 deficiency was studied in atherosclerosis-prone ApoE−/− mice." (PMID 33975450, 2021). "This is consistent with the evidence of a blunted age-dependent increase in the expression of CD200 in the murine aorta in advanced atherosclerosis." (PMID 33975450, 2021). "This is the first study to reveal a role for the CD200/CD200R pathway in atherosclerosis and in the regulation of monopoiesis in hypercholesterolemia." (PMID 33975450, 2021). "Among other immune checkpoints, the CD200/CD200R pathway has the ability to deliver a selective inhibitory signal to monocyte-macrophages that are key cellular culprits in atherosclerosis." (PMID 33975450, 2021). "The CD200 checkpoint is a key-limiting factor for monopoiesis, monocyte-macrophage activation, and recruitment in atherosclerosis with conserved features in human and mouse." (PMID 33975450, 2021). "In conclusion, our data demonstrate that the CD200 checkpoint exerts a more pervasive control of myeloid functions than previously thought and can act at the level of monocyte supply and recruitment thereby reducing atherosclerosis progression." (PMID 33975450, 2021).
celiac disease (1 paper, 2024). An autoimmune genetic disorder with an unknown pattern of inheritance that primarily affects the digestive tract. "We have focused on the alteration of the CD200/CD200R pathway and Elafin expression in celiac disease and discussed their roles in regulating the immune response." (PMID 38255930, 2024).
cerebral infarction (1 paper, 2020). An ischemic condition of the brain, producing a persistent focal neurological deficit in the area of distribution of the cerebral arteries. "We also detected the effect of CD200/CD200R signaling on the size of cerebral infarction." (PMID 32473633, 2020). "The result shown that CD200/CD200R signaling pathway modification did not influence the size of cerebral infarction at 28 days after MCAO (group main effect, F4, 30 = 66.06, P < 0.0001)." (PMID 32473633, 2020).
Chronic colitis (1 paper, 2016). A chronic inflammatory disease of the large intestine (colon, cecum and rectum). "In summary, our data argue strongly for an important role for CD200 overexpression in regulation of gut inflammation, in animals suffering from both acute and chronic colitis." (PMID 26841120, 2016). "Colonic cytokine expression patterns were compared among the four experimental groups to assess the influence of CD200 over-expression on cytokine production in chronic colitis." (PMID 26841120, 2016). "We show that over-expression of CD200 protected mice from DSS-induced acute or chronic colitis, and in our hands mice lacking a functional CD200 signal (CD200KO or CD200R1KO mice) displayed more severe clinical and histological changes compared with WT mice." (PMID 26841120, 2016). "In chronic colitis, by contrast, in addition to myeloid cell infiltration, an increased CD3+ cell infiltration was observed in the colon which was ameliorated in CD200tg mice by over-expression of CD200." (PMID 26841120, 2016).
cognitive decline (1 paper, 2024). "In the present study, mediation model analysis of patients with AD showed that peripheral CD200 mediated neuroinflammation, Aβ deposition and cognitive decline in AD." (PMID 37801139, 2024).
Cognitive impairment (1 paper, 2022). Abnormal cognition is characterized by deficits in thinking, reasoning, or remembering. "Increased CSF-EVs expressing GFAP and CD200 were found in the cognitive impairment group compared to the normal cognition group." (PMID 36601110, 2022). "However, we found a significant increase in CSF-EVs expressing two of the neuronal-associated markers, GFAP and CD200, in HIV+ individuals with cognitive impairment group compared to those without cognitive impairment." (PMID 36601110, 2022).
coronary artery disease (1 paper, 2021). "Mass cytometry in patients with coronary artery disease showed that, among blood leukocytes, B cells display the highest expression of CD200." (PMID 33975450, 2021). "Using a system biology approach, Huan et al6 identified CD200 as one of the top 10 putative key regulatory genes for changes in peripheral blood gene expression in coronary heart disease." (PMID 33975450, 2021). "Multiparameter mass cytometry and high-dimensional analysis were then used to profile CD200 and CD200R expression in circulating immune cell subsets from patients suffering from coronary artery disease (CAD)." (PMID 33975450, 2021).
dermatitis (1 paper, 2021). An inflammatory process affecting the skin. "What is more, a correlation between serum level of soluble CD200 (sCD200) and severity of dermatitis has been demonstrated." (PMID 33804413, 2021).
embryonal carcinoma (1 paper, 2019). A non-seminomatous malignant germ cell tumor characterized by the presence of large germ cells with abundant cytoplasm resembling epithelial cells, geographic necrosis, high mitotic activity, and pseudoglandular and pseudopapillary structures formation. "Furthermore, we tested whether CD200 was involved in EMT and invasiveness in NTERA-2 cells derived from a malignant embryonal carcinoma and endogenously overexpressing CD200." (PMID 31627350, 2019).
eosinophilia (1 paper, 2021). "Treatment with CD200-Fc reduced abrogated inflammatory eosinophil recruitment, and thus reduced eosinophilia in BAL fluid and reduced the number of human ILC2s in the lungs." (PMID 33953190, 2021). "In concurrence with the reduction of AHR and eosinophilia, further histological analyses of the lungs revealed that CD200-Fc treatment after the intranasal challenge reduced the mucous production, abrogated number of infiltrating cells and decreased airway epithelium thickness." (PMID 33953190, 2021). "Challenge with rhIL-33 led to increased eosinophilia and increased human ILC2 numbers in the recipients of isotype control, when compared to CD200-Fc treated group." (PMID 33953190, 2021). "IL-33 challenge led to BAL eosinophilia, increased BAL neutrophils, increased pulmonary ILC2s and thus augmented lung inflammation in isotype-treated cohort, when compared to CD200-Fc-treated mice." (PMID 33953190, 2021).
esophageal adenocarcinoma (1 paper, 2025). A malignant tumor with glandular differentiation arising predominantly from Barrett mucosa in the lower third of the esophagus. "The tumor cells of the neuroendocrine cancer of this latter patient had high expression of CD200 (H-score 155); unfortunately, CD200 could not be assessed in the archival tumor sample of the patient with esophageal adenocarcinoma due to insufficient tumor cells in the sample." (PMID 39651931, 2025).
glomerulopathies (1 paper, 2025). "First, both MCD and MN showed a broadly concordant upregulation of the PD-1/PD-L1, CTLA-4/CD86 and CD200/CD200R axes across all three levels when compared with healthy volunteers, indicating a globally enhanced inhibitory checkpoint tone in primary glomerulopathies." (PMID 41373530, 2025).
helminth infection (1 paper, 2012). "Together these results indicate that, during chronic helminth infection, CD200R and its ligand CD200 are upregulated and co-expressed in chronically activated CD4 T cells." (PMID 22496920, 2012).
Hypercholesterolemia (1 paper, 2021). An increased concentration of cholesterol in the blood. "Nevertheless, during hypercholesterolemia and/or inflammation, CD200 deficiency dysregulates myelopoiesis." (PMID 33975450, 2021).
intracerebral hemorrhage (1 paper, 2023). A cerebrovascular disorder characterized by bleeding into one or both cerebral hemispheres including the basal ganglia and the cerebral cortex. "In contrast, the reduced expression of CD200 and CD200R1 has been observed after intracerebral hemorrhage, and CD200Fc administration could attenuate BBB leakage and improve neurological functions." (PMID 37391731, 2023).
marginal zone lymphoma (1 paper, 2025). A usually indolent mature B-cell lymphoma, arising from the marginal zone of lymphoid tissues. "In this case, despite CD23 negativity, CD43, CD200, and LEF1 positivity support the diagnosis of CLL/SLL, whereas cyclin D1 and SOX11 negativity and LEF1 positivity exclude mantle cell and marginal zone lymphoma, respectively." (PMID 40893576, 2025).
mucositis (1 paper, 2017). Mucositis is inflammation and damage of the mucous membranes lining the mouth and other parts of the gastrointestinal (GI) tract. "The levels of CD22 and CD200 expression were independent of the mucositis grade." (PMID 28052121, 2017).
osteoarthritis (1 paper, 2022). A noninflammatory degenerative joint disease occurring chiefly in older persons, characterized by degeneration of the articular cartilage, hypertrophy of bone at the margins and changes in the synovial membrane. "Modulating other aspects of the dosing regimen and timepoint of analysis may be considered in future exploration of CD200 based therapeutics for osteoarthritis." (PMID 35359946, 2022).
pancreatic neuroendocrine cancer (1 paper, 2025). "A confirmed partial response was observed in a participant with well-differentiated pancreatic neuroendocrine cancer whose tumor was among those with the highest tumor CD200 expression." (PMID 39651931, 2025).
parasite infection (1 paper, 2018). "Therefore, we first analyzed the effect of CD200 expression on DCs upon parasite infection on proliferation and function of T cells." (PMID 29915577, 2018).
peritoneal adhesions (1 paper, 2020). "Significantly higher percentages of CD19+/CD200+ B lymphocytes, CD8+/CD200+ T lymphocytes, and CD8+/CD200R+ T lymphocytes were found in patients with EMS and concomitant adhesions (p = 0.024, p = 0.0056, and p = 0.024, respectively) compared with those with EMS but without peritoneal adhesions." (PMID 32967175, 2020).
pneumonia (1 paper, 2020). An acute, acute and chronic, or chronic inflammation focally or diffusely affecting the lung parenchyma, caused by an infection in one or both of the lungs (by bacteria, viruses, fungi, or mycoplasma.). "The CD200−/− mice develop ALI during pneumonia due to the increased pro-inflammatory function of macrophages and a decrease in the resolution of inflammation." (PMID 32849610, 2020).
prion disease (1 paper, 2011). A transmissible disease that is caused by a protein that is able to induce abnormal folding of normal cellular proteins, leading to characteristic spongiform brain changes, which are associated with neuronal loss without an inflammatory response. "There is no report about the expression levels of CD200R or CD200 in patients with prion disease, but activated microglia are thought to be related to up-regulation of CD200R4 in a mouse model of prion disease." (PMID 22053982, 2011).
proliferative glomerulonephritis (1 paper, 2016). A constellation of renal disorders characterized by an increase number of cells in the glomerulus; these disorders generally present with nephrotic syndrome, and generally progress to end stage renal failure over a matter of weeks to years, depending on the etiology. "For the CD200-Fc group, the histopathology of proliferative glomerulonephritis was ameliorated with lower PAS scores (1.80 ± 0.45 vs." (PMID 27545083, 2016). "For the CD200-Fc group, the histopathology of proliferative glomerulonephritis was ameliorated, with lower PAS scores compared with the NZB/WF1 group." (PMID 27545083, 2016).